MYCN (MYCN proto-oncogene, bHLH transcription factor)
Diseases named in the same sentence as MYCN in open-access papers (continued):
Sharing a sentence is not in itself a finding about the gene and the disease.
neuroblastoma (continued). "And transfection of SH-EP neuroblastoma cell lines with MYCN has also been shown to induce the up-regulation of several genes involved in glycolysis." (PMID 18789162, 2008). "Amplified MYCN oncogene resulting in deregulated MYCN transcriptional activity is observed in 20% of neuroblastomas and identifies a highly aggressive subtype." (PMID 18851746, 2008). "The most aggressive neuroblastomas are characterized by diverse genetic aberrations, including MYCN amplification, chromosome 1p deletion and unbalanced gain of chromosome 17q." (PMID 18493594, 2008). "From experiments in neuroblastoma cell lines, it is known that MYCN and c-MYC control their expression via autoregulatory loops and via repressing each other at defined promoter sites." (PMID 18851746, 2008). "Several studies have shown a strong correlation between MYCN amplification and deletion of the short arm of chromosome 1, another frequent abnormality in neuroblastomas." (PMID 18493581, 2008). "In primary neuroblastoma, the majority of cases show a rise of miR-17-5p level leading to p21 downmodulation, which is particularly severe in patients with MYCN amplification and poor prognosis." (PMID 18493594, 2008). "In MYCN-amplified neuroblastoma MYCN transactivates miR-17-5p, which in turn accelerates cell cycle progression by downmodulating p21 and protects cells from apoptosis by inhibiting BIM expression." (PMID 18493594, 2008). "In line with these clinical observations, we observed that, in neuroblastoma cell lines with normal MYCN level, overexpression of miRNA 17-5p-92 cluster, as well as miR-17-5p alone, is able to enhance tumorigenesis." (PMID 18493594, 2008). "MiR-184 was found down regulated in paediatric neuroblastomas with MYCN (NM_005378) amplification and poorer prognoses." (PMID 18478077, 2008). "Altogether these results indicate that, in neuroblastoma cells, MYCN transcriptionally induces the expression of the miRNA 17-5p-92 cluster by directly binding to its promoter." (PMID 18493594, 2008). "Amplification of the proto-oncogene MYCN, which occurs in about one quarter of all neuroblastomas, is correlated with poor prognosis." (PMID 18493581, 2008). "Taken together, these results indicate that the genes from subgroups I and II represent a core set of target genes directly regulated by either MYCN or c-MYC in neuroblastoma cells dependent on which MYC protein is expressed." (PMID 18851746, 2008). "Previous quantitative PCR analyses in a cohort of 117 neuroblastoma patients revealed that mRNA levels of MYCN are significantly lower in stage 4-NA than in stage 4s-NA (p = 0.008) and localized-NA neuroblastomas (stages 1, 2, 3; p = 0.03)." (PMID 18851746, 2008). "Main objective of this study was to confirm that surgery alone is an effective and safe treatment for localised resectable neuroblastoma except stage 2 with amplified MYCN gene (MYCNA)." (PMID 18766186, 2008). "Intriguingly, hierarchical clustering of neuroblastoma cell lines according to the MYCN/c-MYC-binding pattern clearly separated MYCN- and c-MYC-expressing neuroblastoma cell lines." (PMID 18851746, 2008). "Of the 427 children with localised resectable neuroblastoma who were evaluated for MYCN gene status, 16 (3.7%) had abnormal copy numbers of the gene, including 7 stage 1 and 9 stage 2 patients." (PMID 18766186, 2008). "There is strong experimental evidence (ectopic MYCN expression in cell lines, N-myc transgenic neuroblastoma mouse model) that increased MYCN activity is involved in tumor initiation and progression of at least a subset of neuroblastomas." (PMID 18851746, 2008). "In line with this, neuroblastoma cells with elevated MYCN expression retain their capacity to undergo apoptosis or neuronal differentiation." (PMID 18851746, 2008). "Our findings indicate that miR-17-5p is a key factor inducing protection from MYCN-primed apoptosis in neuroblastoma." (PMID 18493594, 2008).
neuroblastoma (continued). "More specifically, amplification of the MYCN oncogene occurs in about 20% of neuroblastoma patients and has been shown to provide important prognostic information." (PMID 21892309, 2008). "The polyclonal antibody against c-MYC also gave positive binding signals for a large set of target gene promoters in neuroblastoma cell lines with high MYCN that lack detectable c-MYC expression (SH-EPMYCN, IMR5/75 and Kelly)." (PMID 18851746, 2008). "Despite recent advances in treatment options, aggressive neuroblastoma carrying MYCN amplification is refractory to current therapy, leading to a disease related mortality of up to 70%." (PMID 18493594, 2008). "Here, we defined a core set of MYCN and c-MYC target genes by using oligonucleotide microarrays and a neuroblastoma cell line that allows conditional expression of MYCN or c-MYC." (PMID 18851746, 2008). "Of particular interest is that treatment of MYCN-amplified neuroblastoma with antagomir-17-5p can abolish tumor growth, not only in vitro but also in vivo." (PMID 18493594, 2008). "More recently, profiling of a subset of known miRNAs in neuroblastoma specimens suggested that MYCN acts as a regulator of miRNAs." (PMID 18230126, 2008). "However, MYCN amplification in neuroblastoma causes resistance to chemotherapy, associated with tumor progression and poor prognosis: this suggests that MYCN-induced apoptosis may be inhibited by an additional oncogenic mechanism, crucial for tumor progression." (PMID 18493594, 2008). "Neuroblastoma cell lines with high expression of MYCN as a result of amplification lack c-MYC expression." (PMID 18851746, 2008). "Amplification of the oncogene MYCN in double minutes (DMs) is a common finding in neuroblastoma (NB)." (PMID 18769732, 2008). "We examined ATP and lactate production, oxygen consumption and mitochondrial energisation status for three neuroblastoma cell lines with varying degrees of MYCN amplification and MYCN expression." (PMID 18789162, 2008). "MYCN was the first amplified oncogene with clinical significance identified, and its amplification is highly correlated with advanced neuroblastoma disease stage, aggressive growth and poor prognosis." (PMID 18789162, 2008). "Preliminary results indicate that MYCN binds the p21 promoter, suggesting that in MYCN-amplified neuroblastoma MYCN exerts an additional suppressing activity on p21 expression at transcriptional level (data not shown)." (PMID 18493594, 2008). "Almost all these genes (154 of 167; 92%) showed highest expression in MYCN amplified tumors, suggesting that regulation of these genes by MYCN is similar in neuroblastoma cell lines and tumors." (PMID 18851746, 2008). "As a model for the study of gene amplification in human cancer, we focused on MYCN gene copy alterations in neuroblastoma-derived cell lines." (PMID 17601344, 2007). "The amplicon at 15 Mb contains the MYCN oncogene and its amplification status is used for clinical sub-classification of neuroblastoma." (PMID 17470268, 2007). "As shown by the example of MYCN in neuroblastoma, high-resolution mapping of a particular genome locus is one of the major applications of CGP." (PMID 17601344, 2007). "MYCN amplification has been detected in more than 80% of neuroblastoma cell lines, whereas other regions with high-level genomic amplification have rarely been observed." (PMID 17601344, 2007). "The sole exception to this is the MYCN proto-oncogene, which is markedly amplified and overexpressed in ~22% of neuroblastomas and independently correlates with advanced disease and adverse outcome." (PMID 16822308, 2006). "Neuroblastoma is a frequently lethal pediatric cancer in which MYCN genomic amplification is highly correlated with aggressive disease." (PMID 16822308, 2006). "Retinoid treatment of MYCN transgenic mice bearing neuroblastoma altered the expression of five of nine target genes examined (RARβ2, CYP26A1, CRBP1, DUSP6, PLAT) in neuroblastoma tumour tissue in vivo." (PMID 16012519, 2005).
neuroblastoma (continued). "Neuroblastomas that overexpress MYCN due to amplification of the MYCN oncogene are aggressive tumours that become resistant to chemotherapy." (PMID 15292932, 2004). "Nevertheless, there is controversy over the prognostic importance of MYCN in localised neuroblastoma." (PMID 11953858, 2002). "The 2-OS and 4-OS rates for patients with neuroblastoma with amplified MYCN were 67.1 and 54.4%, respectively, and significantly lower than the 83.8 and 72.0% for patients without MYCN amplification (P=0.0117)." (PMID 11953858, 2002). "In the present study we examined the prognostic value of the INSS, the INPC and biological factors including MYCN amplification, DNA ploidy and 1p deletion in patients with neuroblastoma who underwent treatment between 1995 and 1999." (PMID 11953858, 2002). "Deletion of chromosome arm 1p and amplification of the MYCN oncogene are well-recognized genetic alterations in neuroblastoma cells." (PMID 10604740, 1999). "Neuroblastoma is a heterogeneous childhood tumour of the sympathetic nervous system, in which deletions of chromosomal region 1p and amplification of the MYCN oncogene correlate with aggressive tumour behaviour." (PMID 9667647, 1998). "MYCN amplification or 1p deletion was observed in only 1/27 or 2/17 clinically non-progressing stage 4s tumours respectively, whereas all three progressive stage 4s neuroblastomas showed MYCN amplification, 1p deletion and, in 2/3 cases, distal 17q gains." (PMID 9649137, 1998). "Amplification of MYCN is a widely recognized indicator of poor prognosis in neuroblastoma." (PMID 41673639, 2026). "Leveraging this property, neuroblastoma-derived exosomes can be purified, modified, and loaded with small interfering RNA (siRNA) to silence MYCN expression, combined with chloroquine-an FDA-approved autophagy inhibitor-to simultaneously inhibit autophagy and induce apoptotic signaling." (PMID 41750126, 2026). "11q deletion/MYCN amplification co-occurrence in neuroblastoma (HR = 3.1 for response)." (PMID 41486146, 2026). "In this context, increased MYCN expression, a MYC-family transcription factor implicated in proliferation and differentiation programs in multiple cancers including neuroblastoma, may contribute to the aggressive proliferative phenotype of C2-GBM." (PMID 41614933, 2026). "Left nephrectomy with adrenalectomy revealed stroma-poor, undifferentiated neuroblastoma with regional node involvement and multiple segmental chromosomal aberrations, including 1p and 3p loss, but no MYCN or ALK alterations." (PMID 41749639, 2026). "Analysis of neuroblastoma tumours in which tracRNAs are abundant revealed that low expression of DDX17 and DDX5 genes is associated with high-risk tumours and poor overall patient survival, and inversely linked with MYCN oncogene amplification." (PMID 42209732, 2026). "Together, these findings demonstrate MYCN-dependent effects of TrkC signalling and highlight the therapeutic potential of targeting the PKA pathway to induce differentiation in high-risk MYCN-amplified neuroblastoma." (PMID 41876468, 2026). "Similarly, MYC-family oncoproteins directly occupy the PHGDH promoter, driving overexpression in Group 3 medulloblastoma and MYCN-amplified neuroblastoma." (PMID 41486146, 2026). "Using neuroblastoma cell lines with varying MYCN levels, we found that TrkC activation leads to neuronal differentiation in MYCN non-amplified cells but promotes proliferation in MYCN-overexpressing and MYCN-amplified cells." (PMID 41876468, 2026). "In particular, in neuroblastoma, the MYCN oncogene positively regulates and maintains the expression of RNA isoforms with high ORF dominance, and the expression of high ORF dominance transcripts in neuroblastoma is associated with poor patient prognosis." (PMID 41596295, 2026). "Moreover, higher BMP7 was associated with the shorted event free survival and overall survival of MYCN amplified or stage 4 neuroblastoma." (PMID 41632777, 2026).
neuroblastoma (continued). "In FGFR1N546K;MYCN transgenic mice, neuroblastoma developed within the first days of life, with fatal outcome within 3 weeks, reflecting the devastating clinical phenotypes of patients with FGFR1-mutant, high-risk neuroblastoma." (PMID 41678281, 2026). "Furthermore, gut dysbiosis has emerged as a critical factor influencing tumor progression and diminishing treatment efficacy in MYCN-amplified neuroblastoma." (PMID 41750126, 2026). "KLHL37 inhibitor exerts dramatic antitumor effects against MYCN-amplified neuroblastoma cells." (PMID 40493396, 2025). "Consequently, we also correlated the expression of the shortlisted glycolytic candidates with MYCN mRNA in the SEQC cohort of 498 neuroblastomas." (PMID 41440947, 2025). "Therefore, we propose RTA-408 as a promising drug candidate for fast translational application in treating MYCN-amplified neuroblastoma." (PMID 40493396, 2025). "The present study provides evidence that combining 6-AN with 5-ALA-mediated PDT effectively induces cell death in MYCN-amplified neuroblastoma cells by disrupting redox balance, increasing cellular PpIX accumulation, and subsequent lipid peroxidation of the biomembranes." (PMID 41291487, 2025). "Following the discovery of the MYCN gene and amplification of MYCN in neuroblastoma, MYCN amplification was considered the signature for neuroblastoma, even though only around 20% of neuroblastomas carry amplification of MYCN." (PMID 39802403, 2025). "MIF upregulation in neuroblastoma can induce MYCN expression, resulting in tumor progression." (PMID 39908652, 2025). "Both studies suggest that these EVs may contribute to the aggressive behaviour of MYCN-amplified neuroblastoma." (PMID 41440947, 2025). "Notably, the main conclusion from that study was that it was HIF1α which was predominantly expressed in MYCN-amplified neuroblastoma cells and primary tumors." (PMID 41118218, 2025). "Our study demonstrates that neuroblastoma remains the most frequently encountered tumor type, often with a favorable prognosis due to its potential for spontaneous regression, particularly in low-stage, non-MYCN-amplified cases." (PMID 41007141, 2025). "Furthermore, the combination of CGM097 with venetoclax effectively has suppressed tumor growth in MYCN-amplified neuroblastoma patient-derived xenograft models." (PMID 39802403, 2025). "In addition to MYCN-targeting approaches, small molecule inhibitors can also be used to target other key molecules that affect MYCN stability in neuroblastoma." (PMID 39802403, 2025). "Also, ATP13A3 knockdown appears effective in inhibiting growth in both MYCN‐amplified and non‐MYCN amplified neuroblastoma cell lines." (PMID 39981745, 2025). "Using the expression patterns of only 12 genes from the glycosyltransferase family, we were able to develop a prediction model that forecasts the survival probability of neuroblastoma patients with greater accuracy than the INSS stage, risk status, or MYCN status." (PMID 39860532, 2025). "Consequently, AURKA inhibitors indirectly destabilise MYCN and have shown potent antitumour activity in preclinical models of childhood neuroblastoma." (PMID 41561634, 2025). "The oncoprotein MYCN drives malignancy in various cancer types, including neuroblastoma (NB)." (PMID 40274766, 2025). "Similarly, fimepinostat was evaluated in preclinical models of MYCN amplified neuroblastoma with significant anti‐tumor effects." (PMID 41308010, 2025). "Interestingly, in a previous study the different roles of HIF1α and HIF2α in neuroblastoma with regard to MYCN status and hypoxia was addressed." (PMID 41118218, 2025).
neuroblastoma (continued). "Interestingly, the therapeutic strategy involving combined inhibition of Aurora-A and ATR kinases has shown promise in treating MYCN-amplified neuroblastoma." (PMID 40629041, 2025). "If MYCN levels remain abnormally elevated beyond the developmental window, these progenitor cells fail to mature and instead proliferate uncontrollably, contributing to neuroblastoma formation." (PMID 40365336, 2025). "Likewise, targeting a non-coding region adjacent to MYCN with Cas9D10A led to the rapid depletion of MYCN-amplified neuroblastoma cell lines (SK-N-BE(2 C), KELLY, NGP, CHP-212, and IMR-32) in a dose-dependent manner." (PMID 40456709, 2025). "first identified MYCN, which was amplified in a panel of neuroblastoma cell lines." (PMID 40365336, 2025). "However, the oncogenic impact of MYCN in neuroblastoma is hard to underestimate and the profound reduction in MYCN levels is likely a key factor in the cellular response to the induction of iHIF2α." (PMID 41118218, 2025). "Indeed, a series of mouse studies have demonstrated that MYCN can be an oncogenic driver for glioma, medulloblastoma, primitive neuroectoderm tumor, and neuroblastoma." (PMID 40365336, 2025). "Importantly, our findings in MYCN-amplified neuroblastoma translate to other cancer types with distinct oncogene amplifications." (PMID 40456709, 2025). "Amplification of the MYCN proto-oncogene serves as a key marker of aggressive disease and poor treatment outcomes in certain pediatric tumors originating from the nervous system, including neuroblastoma and medulloblastoma." (PMID 40701975, 2025). "Here, we report that knockdown of ATPase 13A3 (ATP13A3), a member of the P5B‐ATPase polyamine transporter family, limited basal and DFMO‐induced polyamine uptake, attenuated MYCN‐amplified and non‐MYCN‐amplified neuroblastoma cell growth, and potentiated the inhibitory effects of DFMO." (PMID 39981745, 2025). "Expression of MYCN in neuroblastoma cells in which these amino acids were mutated to alanine not only decreased MYCN RNA binding, but also reduced stress resilience to DNA damage during S‐phase." (PMID 40488968, 2025). "This transition is tightly regulated by oncogenic drivers such as neuroblastoma-derived MYC (MYCN), which play a pivotal role in reprogramming gene expression and promoting metabolic reorganization to meet the increased biosynthetic demands of aggressive cancer cells." (PMID 41198652, 2025). "Interestingly, the oncogene MYCN is also part of the CRC, and neuroblastomas with MYCN amplification and high ASCL1 levels exhibit the worst prognosis." (PMID 40527452, 2025). "Moreover, we propose KLHL37 inhibitors as a selective therapeutic strategy for patients with MYCN-amplified neuroblastoma." (PMID 40493396, 2025). "Using anatomical T2-weighted MRI we have previously demonstrated the high chemosensitivity and acute regression of tumours arising in Th-MYCN mice to cyclophosphamide, used for frontline treatment of newly diagnosed neuroblastoma, and in response to other MYCN-targeted therapeutics." (PMID 40359728, 2025). "Therefore, targeting AURKA/B represents a potential strategy for inhibiting MYCN-driven neuroblastoma." (PMID 39802403, 2025). "Notably, CKB and PCSK1N emerged as potential drivers of tumor progression, highlighting their promise as therapeutic targets in MYCN‐amplified neuroblastoma." (PMID 40600620, 2025). "Similarly, MYCN has been shown to undergo phase separation together with MAX to boost transcription of certain genes in neuroblastoma cells." (PMID 40488968, 2025). "Similar to our findings, in a previous study, L1CAM knockdown radiosensitized neuroblastoma cells by simultaneous downregulation of proto-oncogene myelocytomatosis neuroblastoma MycN and the upregulation of tumor suppressor PTEN, which inhibits PI3K/AKT/mTORC1 signaling." (PMID 40429728, 2025). "We next tested whether NIPBL depletion induces neuronal differentiation in MYCN-amplified neuroblastoma cells." (PMID 40867243, 2025).